ENSG00000239079
Synonyms: LOC124902828
Gene: Small nucleolar RNA gene on chromosome 11 (122,726,208 to 122,726,311, reverse strand). Ensembl gene ENSG00000239079.
Gene Ontology:
Biological process: RNA processing
Cellular component: nucleolus
Homologues: Paralogues in human: SNORD13P1 (87% identical), SNORD13 (84% identical), SNORD13D (84% identical), SNORD13P3 (80% identical), SNORD13E (79% identical).